CCR2 (C-C motif chemokine receptor 2)
Diseases named in the same sentence as CCR2 in open-access papers (continued):
Sharing a sentence is not in itself a finding about the gene and the disease.
cancer (continued). "CCL2 binds and activates CCR2 to attract monocytes, basophils, and macrophages to infiltrate TME, thereby promoting cancer cell invasion as well as metastasis." (PMID 39595209, 2024). "We observed that the expression levels of CCR1, CCR2, CCR5, and CCR7 were significantly lower in the HCC tissues in TCGA LIHC dataset and GSE14520 dataset, compared with para-carcinoma tissues." (PMID 38552222, 2024). "Some previous studies have reported that mast cells express different chemokine receptors, such as CCR2, CCR5, CXCR1, or CXCR4, in different cancers (19-, 21)." (PMID 37042867, 2023). "LPS challenge eliminated sevoflurane-induced cancer growth, increased MPO and CCR2 expression and neutrophil infiltration, and reduced pan macrophage infiltration." (PMID 35953652, 2023). "Herein, we examined the effects of CVC on the mRNA and protein levels of CCR2, CCL2, VEGF, NF-κB, c-Myc, IL33, and vimentin, which are involved in the progression of cancer." (PMID 37325423, 2023). "Propagermanium inhibits macrophage migration by inhibiting binding between CCR2 and CCL2, thereby suppressing cancer metastasis." (PMID 36768216, 2023). "In cancer bone metastasis, CCL2 signaling is activated via binding of CCL2 ligand to the CCR2 and CCR4 receptors." (PMID 37607005, 2023). "In particular, chemokines, including CXCL8, CXCL10, CXCL11, CXCL16, CCL26, and CCL7, as well as chemokine receptors, including CXCR3, CCR2, CCR5, and CCR1, were positively correlated with MRPL13 expression in various cancer types." (PMID 37827692, 2023). "Inflammatory CAF-derived factors promote cancer cell migration by stimulating the chemokines CCR2, CCR5, and CXCR1/2 expressed by cancer cells and Ras-activating receptors." (PMID 37978384, 2023). "CCR2 is expressed in monocytes, such as macrophages, and monocytes migrate in response to CCL2 secreted from cancer cells." (PMID 36768216, 2023). "In other cancer types, inhibiting the CCL2/CCR2 axis with CCR2 inhibitors or anti-CCL2 antibodies has demonstrated reduced myeloid cell recruitment and improved clinical outcomes." (PMID 38087370, 2023). "Of several compounds targeting CCL2/CCR2 to enter phase I clinical trials, CCX872, a CCR2-specific antagonist, showed the best anti-cancer activity, although the benefit was still modest." (PMID 37090720, 2023). "MCP-1 is produced by many cancer cells and acts on the very same by signaling through C–C chemokine receptor type 2 (CCR-2, CD192) on CCR-2-expressing cancer cells." (PMID 37849764, 2023). "The importance of the CCL2/CCR2 and CXCL8/CXCR2 axes in various cancers has led to the development of several small-molecule inhibitors that target the two axes." (PMID 36403057, 2022). "In summary, we showed that KRAS-mutant cancer cells express CCL2 and IL1R1 to initiate an inflammatory signaling loop with CCR2/IL-1β-expressing myeloid cells." (PMID 35327394, 2022). "The CCL2/CCR2 and CXCL8/CXCR2 axes play an essential role in the malignant progression of tumors and act as novel targets for cancer treatment." (PMID 36403057, 2022). "Another recent study has shown that CCL16 binds explicitly to CCR2, which in turn activates the AKT/mitogenic effector kinase (GSK3β) signaling and promotes β-catenin nuclear translocation, leading to enhanced cancer cell stemness." (PMID 35281057, 2022). "FAK is among the intracellular pathways that have shown promise as a target in cancer treatment, in addition to other well-known signaling molecules including RAS-RAF-MEK1/2-ERK1/2, CCR2/CCR5, and CXCR4." (PMID 34771675, 2021). "Promising results from PET studies using [68Ga]pentixafor, [64Cu]DOTA-ECL1i, and [64Cu]DOTA-DAPTA-comb expanded the boundaries of cancer and cardiac disorder imaging for CXCR4, CCR2, and CCR5, respectively." (PMID 34500609, 2021). "Therefore, targeting CCR2 might prove a rational approach for preventing cancer metastasis." (PMID 35006432, 2021).
cancer (continued). "In TME, CCR2 interacts with CCL2 to mediate chemotaxis of monocytes and TAMs, which consequently contributes to the shaping of TME and promotes cancer progression and metastasis." (PMID 34251980, 2021). "Recent advances in the development of radiotracers for various chemokine receptors, particularly of CXCR4, CCR2, and CCR5, shed new light on chemokine-related cancer and cardiovascular research and the subsequent drug development." (PMID 34500609, 2021). "It is reported that CCR1, CCR2, CCR3 and CCR5 are involved in CCL7‐mediated macrophage migration and contribute to various inflammatory diseases and cancer." (PMID 34189838, 2021). "Regarding the migration, it has been reported that chemokine/cytokine receptors such as CCR2 and CXCR-4 play key roles in cell migration and metastatic spread in a variety of cancers, including CRC." (PMID 34059044, 2021). "CCL8, also known as MCF2, acts as an agonist of the CC chemokine receptor type 2 (CCR2) and CCR5, exerting significant function in the process of leukocyte chemotaxis, cancer tumorigenesis and progression, and responds to changes in the pathogenic environment." (PMID 33146700, 2020). "Elevated expression of CCR2 and MMP9 in ZEB1 wildtype F4/80low macrophages provided a positive feedback loop with ZEB1 wildtype cancer cells through cancer cell-expressed CCL2 cytokines." (PMID 32283687, 2020). "Features representative of cancer stem cells show that higher expression of STAT3, AHR, and CCR2 modules distinguishes cancer stem-cell samples from their non–stem cancer cell counterparts." (PMID 32383980, 2020). "Another study found that CCL2 binding to CCR2 has led through MEK and ERK activation to increased cancer cell survival, partly through activation of the Rho pathway." (PMID 32582148, 2020). "Our findings indicate that CAF-FAK expression regulates the expression of chemokines Ccl6 and Ccl12, which through malignant cell Ccr1/Ccr2 activity and PKA activation can control cancer cell metabolism." (PMID 32157087, 2020). "CCR2 targeted mAB, MLN1202/plozalizumab (Millenium/Takeda Oncology) has been evaluated in multiple clinical trials for cancer and other indications." (PMID 33329395, 2020). "The role of CCL2 in cancer progression has gradually been understood, and various preclinical cancer models elucidate that CCL2 and its receptor C-C chemokine receptor 2 (CCR2) are attractive targets for intervention in cancer development." (PMID 33297571, 2020). "Targeting chemokine interactions and subsequent recruitment of macrophages within tumors, including the CCL2/CCR2 or CXCL12/CXCR4/7 chemokine-chemokine receptor axes, have shown great potential for cancer therapies in various mouse models of cancer metastasis." (PMID 30832375, 2019). "The percentages of CCR2+ cells in both subsets of CD4+ and CD8+ T lymphocytes were significantly lower in carcinoma tissue as compared with unaffected mucosa." (PMID 29020986, 2017). "Because of its correlation with the progression of cancer, the CCL2/CCR2 signaling pathway has generated increasing interest in the past few years." (PMID 27409666, 2016). "To determine the effect of inhibition of CSF-1 and CCL2 signalling on cancer cells we utilised the small molecule inhibitors of CSF-1R (GW2580) and CCR2 (RS102895)." (PMID 26174804, 2015). "We here report its use as a cancer therapeutic agent targeting tumors expressing CCR2 and provide pre-clinical evidence that this pro-apoptotic fusokine could be of great interest as a lead compound of a new class of biological agents targeting CCR2-expressing malignancies." (PMID 21943176, 2011). "Finally, the promising therapeutic potential of targeting specific chemokine signaling axes, such as CCL2/CCR2 and CXCL10/CXCR3, was discussed as a strategy to improve the efficacy of cancer immunotherapy." (PMID 41635851, 2026).
cancer (continued). "Moreover, TAM recruitment was found to be influenced by immune-related genes such as CCL2, CCR2, CXCR4, and CCR5, which suppress immune responses and facilitate cancer progression." (PMID 39968182, 2025). "Pharmacologically induced CCR2-expressing non-classical monocytes can infiltrate and regress immunotherapy-resistant cancers by recruiting natural killer cells." (PMID 39545417, 2024). "The reason why cancers preferentially metastasize to lung, liver, bone and brain may be due to the presence of CCL2 and CCR2 in these tissues and organs 43, which are chemotactic for TM2 and thus, provides ideal conditions for harboring TM2." (PMID 38356723, 2024). "Consequently, it seems that inhibition of the CCR2_CCL2 signaling pathway can downregulate EMT and reduces cancer progression through the inhibition of transcription factors such as Vimentin." (PMID 37325423, 2023). "Finally, to test the effect of CCR2 inhibitor on the extravasated cancer cells and their potential therapeutic benefit, we started the daily CVC treatment at day 7 after cancer cell inoculation." (PMID 37149684, 2023). "Moreover, TAM recruitment depends on immune-related genes such as CCL2, CCR2, CXCR4, and CCR5, which can promote cancer development by promoting immunosuppression." (PMID 37275880, 2023). "Although anti-CCL2 antibodies and CCR2 antagonists have been tested in clinical trials, one study reported that the interruption of anti-CCL2 antibody treatment markedly increased lung metastasis and accelerated death in mouse syngeneic cancer models." (PMID 37865750, 2023). "Such strategies were based on the benefit of treatment with the RDC018 CCR2 antagonist, which induced anti-cancer CD8 T-cell responses, or a natural-tree-derived CCR2 antagonist, which was efficient alone and potentiated the effect of the sorafenib kinase inhibitor." (PMID 35159113, 2022). "The inability of each receptor to compensate for the absence of the signals delivered by the other receptors suggests that all receptors, CXCR1/2 + CCR2 + CCR5, needed to be activated simultaneously in order to mediate the intrinsic signals of WT-PD-L1 that lead to increased cancer cell invasion." (PMID 35205789, 2022). "Fibrocytes that were identified in lung tumors as CD45+CD44+CD162+CD11b+F4/80+CCR2/5+CD9+ cells had lost the monocyte marker Ly6C compared to bone marrow fibrocytes, indicating a maturation process in the cancer microenvironment, reminiscent of monocyte to macrophage differentiation in tumors." (PMID 36241617, 2022). "Therefore, the nerve-released CCL2 interacts with cancer cell CCR2 to promote PNI and this CCR2-mediated signaling links to the MAPK and Akt pathway activity." (PMID 36077602, 2022). "Similarly, this pathway was also shown to be involved in the recruitment of type I cytotoxic γδ T cells in melanoma tumors, a hybrid NK/CD8 T lymphocyte able to kill cancer cells, thus conferring an antitumor role of CCL2/CCR2." (PMID 36429101, 2022). "As CCL2/CCR2 activated SRC and SRC interacts with MET to regulate receptor activation in carcinoma cells, we asked whether CCL2-mediated SRC activation was important for MET phosphorylation." (PMID 35405500, 2022). "It is noteworthy in this respect, that the genes showing the strongest signals of negative selection include several plasma membrane receptor proteins (e.g. ACKR3, CCR2, CCR5, CX3CR1, TBXA2R) that cancer cells utilize to promote migration, invasion, and metastasis." (PMID 33427197, 2021). "Among these chemotactic signals, the CCL2/C-C chemokine receptor type 2 (CCR2) signal axis is the most crucial chemokine signaling pathway on which monocyte recruitment depends and is widely used a target in TAM research and cancer treatment." (PMID 33919979, 2021). "As pro-metastatic γδ T cells also express CCR2,83,85,86 inhibitors of CCL2 or CCR2 could be beneficial for targeting cancer types that rely on monocytes or γδ T cells or both." (PMID 33262520, 2021).
cancer (continued). "In addition, shRNAs targeting CCR2 and XAV939 targeting β-catenin abolished CCL16-mediated cancer stemness." (PMID 33500726, 2021). "In this study, through the analyze of the data from the Gene Expression Omnibus, the Cancer Genome Atlas and the Genotype-Tissue Expression, we found that the expression of KLRG1, BTK, CCR2 and SCML4 was significantly downregulated in LUAD tissues compared to normal controls." (PMID 34187403, 2021). "In addition, shRNA silencing CCR2 and XAV939 (a β-catenin inhibitor) both abolish CCL16-mediated cancer cell stemness." (PMID 33500726, 2021). "Despite the setbacks in development of CCL2/CCR2 in clinical studies, particularly for inflammatory conditions, the detrimental roles of the CCL2/CCR2 axis in cancer setting have increasingly been appreciated so that the CCL2/CCR2 axis remains to be actively targeted as candidates for immunotherapy." (PMID 34804061, 2021). "In addition, we found significant downregulation of multiple cancer-related genes coding for cytochrome P450 1B1 (CYP1B1), C-C chemokine receptor type 2 (CCR2), stabilin-1 (STAB1) and transmembrane protein 176B (TMEM176B)." (PMID 32780768, 2020). "There is an increasing evidence to the vital anti-proliferative effects of bevacizumab (avastin; AV) and CCR2 antagonist (CR), and recently their PLGA-based and micelles-based nanoparticulates (NPs) on different cancer cells." (PMID 31350989, 2019). "Inhibition of CCR2/CCL2- and CSF-1R-dependent signaling pathways is a major focus in this field, as direct targeting of CCR2/CCL2 showed positive outcomes in various experimental cancer models." (PMID 31547627, 2019). "This not only could contribute to cancer formation, but also to tumor aggression via production of MCP-1/CCR-2, and induction of cancer stem cell (CSC) metastasis." (PMID 29385712, 2018). "Across all subtypes, we found that dual positive (CD14+/CCR2+) cells were almost three times more abundant in the stromal (pan-CK negative) regions than in the cancer cell islet (pan-CK positive) regions." (PMID 29777108, 2018). "Immunity‐associated genes, including chemokine and the chemokine receptors CCR2,36, 37, 38CCR7,39 and CXCL940 are well‐documented oncogenes in numerous cancers and are involved in mediating the crosstalk between tumors and their microenvironment, as well as in promoting metastasis." (PMID 30117304, 2018). "As studied extensively, Tregs isolated from healthy donors and cancer patients can express a plethora of chemokine receptors (CCR2-9, CXCR3/4) and migrate efficiently in vitro in response to tumor-derived chemokines, typically secreted by cancer cells or innate immune cells." (PMID 27509527, 2016). "We found blockade of EGF/EGFR axis reduced the expression of CCL2 in Cal27 cells, while suppression of CCL2/CCR2 axis decreased the expression of EGF in THP1 cells, suggesting that in HNSCC, the crosstalk between cancer cells and macrophages was also mediated by a positive feedback paracrine loop." (PMID 27888616, 2016). "However, we did not observe a ZEB1-dependent effect on proliferation of CD8 + T cells in vitro when co-cultured with BMDMs, but a ZEB1-dependent modulation of CD8 + T cell migration by CCL2 and CCL22 as well as CCR2 and CCR4 expression in CD8 + T cell subsets in murine and human cancers." (PMID 40595293, 2025). "In addition, given the correlation between the density of TAMs and cancer prognosis, blocking the recruitment of macrophages in TME, for instance through ablation of CCL2/CCR2 axis, has been shown to be an effective therapeutic strategy to reduce the density of protumor TAMs and improve prognosis." (PMID 39003350, 2024). "Considering the significant role of the CCR2 receptor in cancer, in this study, for the first time, we studied the effect of this compound in preventing the development of CRC in mouse models and cell lines through inhibition of the CCR2_CCL2 signaling pathway." (PMID 37325423, 2023).
cancer (continued). "Interestingly, the expression of CD206, CD86, CCR2 and C1QC expression in the Apoe-/- mice non-cancer model compared with Apoe+/+ mice was also decreased, indicating that changes in macrophages in the spleen and TAM might be consistent." (PMID 36147474, 2022). "Because RT can induce immunogenic cell death in cancer cells, and it is well established that immune cells are crucial for the antitumor effect of RT, we decided to investigate both GVAX and RT as T cell–priming agents in combination regimens that included αPD-1 and CCR2/5i in mouse models of PDAC." (PMID 35404390, 2022). "Not surprisingly, AML patients (65%) also had CCR2 expressing cancer cells." (PMID 34804061, 2021). "In summary, to achieve sufficient efficacy of CCL2–CCR2-targeted therapy for cancer patients, it is not sufficient to target cancer cells or immune cells alone and it is necessary to fully elucidate the physiological functions of the CCL2–CCR2 axis against a variety of normal cells expressing CCR2." (PMID 33297571, 2020). "However, systemic CCR2 inhibition did not reduce the number of early circulating cancer cells (eCCCs) compared to the treatment that blocked the CSF1R, which reduced intra-epithelial macrophages by ~77%." (PMID 29295986, 2018). "However, the usage of CCR2-depleting antibody has not been previously tested in cancer immunotherapy." (PMID 29170400, 2017). "Hence, pharmacological induction of CCR2+ nonclassical monocytes might be useful for immunotherapy-resistant cancers." (PMID 39545417, 2024). "Interestingly, Ccr2 is expressed highly in M2 and TAMs in cancer, but not in TRMs." (PMID 36511483, 2022). "In view of the rather disappointing developmental history of CCR2 antagonism, and the now increased understanding of mode of action of the CCL2/CCR2 axis, we attempt to discuss the strategies that could facilitate tailored application of CCR2 antagonism in cancer therapy." (PMID 34804061, 2021). "Moreover, we demonstrate that CCR2-independent intratumoural F4/80hi macrophages, and not the CCR2-dependent monocytes or monocyte-derived macrophages, support cancer progression, suggesting this particular F4/80hi cell fraction as an attractive therapeutic target." (PMID 29422500, 2018). "In the metastatic site, the PV macrophage subset, which expresses CCR2 and VEGFA (but not TIE2), promotes cancer cell seeding through direct interactions with cancer cells at the vessel wall and subsequently promotes colonization." (PMID 39516356, 2024). "CCR2 was expressed on more than 60% of monocytes of classical CD14+CD16- subset, and the minimal expression level of CCR2 was observed in non-classical CD14-CD16+ subset in both healthy donors and cancer patients." (PMID 36733385, 2022). "Finally, conditioning of WT mice with CCL2-conjugated exosomes, followed by injection of syngeneic cancer cells, led to a significant (p < 0.05) increase in lung metastasis formation compared to non-conjugated exosomes, while no impact on BC metastasis was noticed in the lungs of CCR2−/− mice." (PMID 34112803, 2021). "IHC staining of CCR2 protein was performed on tissue sections from 16 human normal cervical samples, 20 cervical non-PNI cancer samples, and 20 with PNI." (PMID 32064233, 2020).